IDH1 (isocitrate dehydrogenase (NADP(+)) 1)
Diseases named in the same sentence as IDH1 in open-access papers (continued):
Sharing a sentence is not in itself a finding about the gene and the disease.
endometrial cancer (9 papers, 2016 to 2024). Primary or metastatic malignant neoplasm involving the endometrium (mucous membrane that lines the endometrial cavity). "We next sought to investigate how IDH1 T77 phosphorylation reduces progestin sensitivity in endometrial cancer cells." (PMID 38582508, 2024). "In endometrial cancer cells bearing WT IDH1, the proliferation was higher and apoptosis was lower at enhanced stiffness, which was rescued by reconstituted expression of IDH1 T77A." (PMID 38582508, 2024). "Accordingly, endometrial cancer cells expressing WT IDH1 exhibited treatment resistance on 2D ECM proteins." (PMID 38582508, 2024). "The study reports a previously unrecognized link between IDH1 T77 phosphorylation and progestin resistance in endometrial cancer." (PMID 38582508, 2024). "Our results revealed that MPA, in combination with focal adhesion inhibitors or p38 inhibitor markedly induced apoptosis in endometrial cancer cells, suggesting the suppression of focal adhesions or IDH1 phosphorylation improved MPA efficacy." (PMID 38582508, 2024). "We provide evidence that IDH1 T77 phosphorylation (pT77‐IDH1) is induced by p38 in response to progestin in endometrial cancer cells, which enhances IDH1 enzymatic activity and facilitates its nuclear redistribution." (PMID 38582508, 2024). "In conclusion, we report a previously unrecognized link between IDH1 T77 phosphorylation and progestin resistance in endometrial cancer." (PMID 38582508, 2024). "We then depleted IDH1 in endometrial cancer cells and rescued these cells with Flag‐tagged shRNA‐resistant (r) IDH1 wild‐type (WT), T77A and T157A, and found that only the T77A mutation failed to be phosphorylated after MPA administration." (PMID 38582508, 2024). "The IDH1 T77A mutation notably attenuated endometrial cancer cell viability upon MPA exposure and displayed half maximal inhibitory concentration (IC50) values much lower than those of WT IDH1 control cells." (PMID 38582508, 2024). "In endometrial cancer cells where NR4A1 is silenced, the major source of ROS is associated with the downregulation of TXNDC5 and IDH1." (PMID 39000233, 2024). "Isocitrate dehydrogenase 1- (IDH1) mediated chemoresistance in endometrial cancer cells can be abated by metformin treatment, which inhibits the IDH1-induced NRF2 expression." (PMID 34065108, 2021). "We found that IDH1 is overexpressed in endometrial cancer tissue and plays an essential role in chemoresistance." (PMID 33041661, 2020). "In a similar context, very recent data from Bai and coworkers demonstrated that the enzyme isocitrate dehydrogenase 1 (IDH1) was highly expressed and aberrantly activated in endometrial cancer tissues and lines, promoting chemoresistance." (PMID 31097977, 2019). "Inhibition of IDH1 T77 phosphorylation or focal adhesion signaling may hold therapeutic potential to treat progestin‐resistant endometrial cancer." (PMID 38582508, 2024). "MPA treatment increased the phosphorylation of endogenous and exogenous IDH1 in Ishikawa and HEC1‐A endometrial cancer cells." (PMID 38582508, 2024). "Importantly, Metformin was shown to disrupt this regulatory loop repressing the IDH1/α-KG-dependent activation of TET1 and attenuating the hydroxymethylation levels of the NRF2 promoter, ultimately restoring the chemosensitivity of various endometrial cancer cells." (PMID 31097977, 2019).
gliosarcoma (9 papers, 2015 to 2025). A rare histological variant of glioblastoma (WHO grade IV) characterized by a biphasic tissue pattern with alternating areas displaying glial and mesenchymal differentiation (WHO). "Patient 8 (imaging not displayed), a 53 year-old man, originally had a right frontal gliosarcoma (IDH1/2 wild type, methylated MGMT promoter)." (PMID 29113409, 2017). "This sample was unique among the IDH1 mt tumors as it represented a GBM with gliosarcoma phenotype." (PMID 29428975, 2018).
brainstem gliomas (8 papers, 2016 to 2026). "Here, we reported five patients with IDH1 mutations associated with brainstem gliomas, including four cases of IDH1 R132H mutations and one case of R132G mutation." (PMID 35991838, 2022). "Consistent with our previous study on resectable brainstem gliomas, IDH1 and H3.3 mutations were mutually exclusive." (PMID 29137285, 2017). "Of the 13 adult brainstem gliomas that underwent whole exome sequencing in this study, 5 (38%) were IDH1 mutated." (PMID 27556016, 2016). "This indicates age is a key factor in developing brainstem glioma with IDH1 mutation." (PMID 32555164, 2020). "Therefore, TMZ-based chemotherapy would be effective in adult brainstem gliomas, especially for the adult patients with IDH1-mutated tumors." (PMID 29137285, 2017). "Taken together, resectable malignant brainstem gliomas can be classified into three subtypes: H3F3A-mutated, IDH1 mutated and H3F3A-IDH1 co-wildtype tumors, which have distinct clinical characteristics, prognoses, genetic and immune features." (PMID 29137285, 2017). "Resectable malignant brainstem gliomas can be classified into three subtypes: H3F3A-mutated, IDH1 mutated and H3F3A-IDH1 co-wildtype tumors, which have distinct clinical characteristics, prognoses, genetic and immune features." (PMID 29137285, 2017). "Detection of 2HG by MRS and molecular analysis, including non-canonical IDH1/2 mutations, were helpful in determining treatment response in this adult brainstem glioma case." (PMID 40697380, 2025). "These typical cases suggest that adult IDH1-mutant brainstem gliomas have different clinicopathological and genetic characteristics, some of which may be associated with poor prognosis." (PMID 35991838, 2022). "IDH1 mutations are the most frequent mutations in supratentorial gliomas, but were not as frequent in the brainstem gliomas (9, 14.5%)." (PMID 29137285, 2017). "The factors of patients’ age, KPS level before operation, WHO malignancy grade, receiving radiotherapy after operation, genetic mutations in IDH1 and H3.3, and high density of CD8+ T cell infiltration, significantly affect the overall survival of brainstem glioma patients." (PMID 29137285, 2017). "A couple of studies have shown that mutations in IDH1 and IDH2 genes can be found in 18-31% of adult brainstem gliomas and that a majority of these mutations are non-canonical IDH1/2-mutations, compared to a high frequency of IDH1 R132H mutations in IDH-mutant supratentorial diffuse gliomas." (PMID 40697380, 2025). "Indeed, some of these conditions even involve the same genes, an example being that biallelic mutations in IDH1 cause hydroxyglutaric aciduria, whereas mono-allelic hypermorphic mutations cause a druggable form of brainstem glioma." (PMID 32054038, 2020).
brainstem gliomas (continued). "These mutations were previously thought to be uncommon in adult brainstem glioma, as studies of pediatric DIPG did not identify any such mutations, and IDH1 R132H mutations as detected by immunohistochemistry were found in only 6% of the adult brainstem gliomas in one study." (PMID 27556016, 2016). "Studies have shown that as high as 31% of adult brainstem gliomas are IDH mutant, with most of these mutations being non-canonical IDH1/2 mutations." (PMID 40697380, 2025). "However, in our previous study, only 33 cases of brainstem gliomas were included, the clinical characteristics of IDH1 or H3.3-mutated subtypes were not described, and overall survival rates were not significantly different for individuals with H3.3-mutated and IDH1-mutated brainstem gliomas." (PMID 29137285, 2017).
ganglioglioma (8 papers, 2017 to 2026). A well differentiated, slow growing neuroepithelial neoplasm composed of neoplastic, mature ganglion cells and neoplastic glial cells. "Among these, we identified six cases of H3F3A-mutant ganglioglioma and six cases that had both H3F3A and IDH mutations (4 IDH1 R132H and 2 IDH2 R172C)." (PMID 37524847, 2023).
liver cancer (8 papers, 2018 to 2025). An epithelial or non-epithelial malignant neoplasm that arises from the liver. "In conclusion, these data suggest that activating IDH1 is a potential anti-liver cancer strategy and that IDH1 is a potential antitumor target for Scu." (PMID 38622131, 2024). "As the first small molecule that can activate IDH1, Scu can be used to inhibit the progression of liver cancer." (PMID 38622131, 2024). "The CRISPR liver cancer database was used to construct scatter plots showing that IDH1 protein expression was negatively correlated with the expression of HIF1a in HCC cells." (PMID 38622131, 2024). "There is a growing body of evidence of the use of metabolomics for diagnosis and therapy of liver cancers, especially with metabolites of TCA cycle, miRNA, IDH1 and IDH2." (PMID 36768732, 2023).
diffuse midline glioma (7 papers, 2018 to 2025). A diffuse glioma that arises from the midline structures of the central nervous system. "We will specifically elaborate on diffuse pediatric-type high-grade glioma (pDHGG) H3 wild-type and IDH1 wild-type, diffuse hemispheric glioma H3G34-mutant (H3 G34-mutant DHG), and diffuse midline glioma H3K27-altered (H3 K27-altered DMG)." (PMID 40075726, 2025).
metastatic disease (7 papers, 2015 to 2023). "The attributes associated with an increased risk of death included higher ECOG performance status, larger tumors, metastatic disease at the time of RT, the presence of portal vein thrombus, the presence of satellite lesions, IDH1 mutation, and PIK3CA mutation." (PMID 34945742, 2021). "Although metastatic tumors display a significantly higher rate of CNAs and mutation frequencies, the subtype distribution remained fairly similar, except for the scarcity of IDH1 mutation in metastatic tumors." (PMID 29690565, 2018). "We also found that the time interval between diagnosis and detection of metastatic disease six months following presentation of the primary tumour was shorter in IDH2 tumours compared to IDH1 (p = 0.04)." (PMID 36042521, 2022). "Upon multivariable analysis, the factors associated with death included worse performance status, larger tumor, metastatic disease, higher CA 19-9, PVT, satellitosis, and IDH1 and PIK3CA mutations." (PMID 34945742, 2021).
Obesity (7 papers, 2014 to 2026). Accumulation of substantial excess body fat. "These two mouse models highlight the potential for IDH1 to promote induction of fatty liver, hyperlipidemia, and obesity by altering lipid biosynthesis in the liver, especially under HF-induced stress." (PMID 34879063, 2021). "IDH1 plays a vital role in the regulation of lipogenesis and metabolism, and the phenotypes of transgenic mice that overexpress IDH1 include fatty liver, hyperlipidemia, and obesity." (PMID 24983750, 2014). "miR-181c can attenuate lipid biosynthesis by directly binding to the 3′-UTR of IDH1 mRNA and perhaps overexpressing miR-181c in liver may play that therapeutic approach against obesity." (PMID 34879063, 2021). "IDH1 primarily exerts metabolic effects in vivo, IDH1 ectopic expression suppresses the production of brown adipocytes as a novel therapeutic target against obesity and related metabolic diseases such as type II diabetes and may represent a therapeutic target for the treatment of metabolic diseases." (PMID 37645416, 2023).
α-thalassemia (7 papers, 2020 to 2023). "Nuclear expression of ATRX (nuclear immunopositivity for α-thalassemia/mental-retardation-syndrome-X-linked) was retained, and there was expression of IDH1 (isocitrate dehydrogenase 1) R132H mutant protein." (PMID 35018523, 2022). "Apart from that of the known molecular marker IDH1, we found that the status of cell division cycle 27 (CDC27), podocon (PODN), α-thalassemia/mental retardation syndrome X-linked (ATRX) and ryanodine receptor type 1 (RYR1) was significantly different between the two subgroups (P<0.05)." (PMID 34025640, 2021). "Nuclear expression of ATRX (nuclear immunopositivity for α-thalassemia/mental-retardation-syndrome-X-linked) was retained and there was no expression of IDH1 (isocitrate dehydrogenase 1) R132H mutant protein." (PMID 32451719, 2020).
acute leukemia (6 papers, 2020 to 2026). A clonal (malignant) hematopoietic disorder with an acute onset, affecting the bone marrow and the peripheral blood. "This study aimed to identify the prevalence of IDH1/2 mutations in acute leukemia patients." (PMID 34946913, 2021).
anemia (6 papers, 2018 to 2023). A reduction in the number of red blood cells, the amount of hemoglobin, and/or the volume of packed red blood cells. "A recent study revealed that the IDH1 mutation was associated with myeloid dysplasia in mice, which exhibited anemia, ineffective erythropoiesis, and increased immature progenitors and erythroblasts." (PMID 35566503, 2022). "Logistic regression analysis identified IDH1, ASXL1 and SRSF2 mutations, very high-risk karyotype, age > 70 years, male sex, circulating blasts ≥ 3%, presence of moderate or severe anemia and constitutional symptoms, as predictors of LT in the first 5 years of diagnosis." (PMID 30683837, 2019). "Time-to-event Cox analysis confirmed LT prediction for IDH1 mutation (HR 4.3), circulating blasts ≥ 3% (HR 3.3), SRSF2 mutation (HR 3.0), age > 70 years (HR 2.1), ASXL1 mutation (HR 2.0) and presence of moderate or severe anemia (HR 1.9)." (PMID 30683837, 2019). "A parallel time-to-event Cox analysis confirmed inferior LFS in patients with IDH1 mutation (HR 4.3), SRSF2 mutation (HR 3.0), ASXL1 mutation (HR 2.0), circulating blasts ≥ 3% (HR 3.3), age > 70 years (HR 2.1), and presence of sex-adjusted moderate or severe anemia (HR 1.9)." (PMID 30683837, 2019). "IDH1/2 is a gene involved in methylation and DNA damage: knock-in mice for IDH1/2 showed higher hematopoietic stem and progenitor cells (HSPC) proliferation, intense anemia, and extramedullary disease." (PMID 34684081, 2021).
chronic myelomonocytic leukemia (6 papers, 2012 to 2023). A myelodysplastic/myeloproliferative neoplasm which is characterized by persistent monocytosis, absence of a Philadelphia chromosome and BCR/ABL fusion gene, fewer than 20 percent blasts in the bone marrow and blood, myelodysplasia, and absence of PDGFRA or PDGFRB rearrangement. "As a consequence of uncontrolled disease, she progressed to a chronic myelomonocytic leukemia-like (CMML) accelerated phase (AP) disease with the acquisition of a mutation in IDH1." (PMID 37746298, 2023). "We also searched for TET2, DNMT3A, ASXL1, EZH2, IDH1/2 and CBL gene families mutations, given their potential clinical importance in diseases closely associated with SM like primary myelofibrosis, chronic myelomonocytic leukemia (CMML) and others." (PMID 22905207, 2012). "Furthermore, while TET2 mutations are more frequent in chronic myelomonocytic leukemia (CMML) than in AML, IDH1/2 mutations are more common in AML than in CMML." (PMID 33805247, 2021). "The IDH1 inhibitors olutasidenib and LY3410738 are being evaluated for AML (NCT02719574) and chronic myelomonocytic leukemia (CMML)/AML treatment, respectively (NCT04603001)." (PMID 36050788, 2022).
myelofibrosis (6 papers, 2016 to 2025). A partial or complete replacement of the bone marrow stroma by fibrous tissue. "In more details, NFE2, SRSF2 and EZH2 were associated with secondary myelofibrosis, while SRSF2 and IDH1/2 were associated with AML/MDS transformations." (PMID 40533498, 2025). "A total of 38 IDH mutations (19 IDH2 R140, 18 IDH1 R132 and one IDH2-R172) were described: five ET (0.8%), eight PV (1.9%), 13 PMF (4.2%), one post-PV/ET myelofibrosis (1%) and 11 blast-phase MPN (21.6%)." (PMID 26668680, 2016). "In another study, 166 patients with chronic-phase MPN (77 PMF, two post-PV myelofibrosis, two post-ET myelofibrosis, 47 ET, and 38 PV) and 34 blast-phase MPN were screened for IDH1 and IDH2 mutations." (PMID 26668680, 2016). "The multivariate analysis of all parameters under study clearly showed that the presence of so-called high risk mutations in ASXL1, EZH2, IDH1/2, or SRSF2 is not able to predict progression to myelofibrosis (p = 0.99)." (PMID 33541399, 2021). "The largest study that investigated the frequency of IDH1 and IDH2 mutations in Ph-negative MPN patients included 594 ET, 421 PV, 312 PMF, 95 post-PV/ET myelofibrosis and 51 blast-phase MPN patients." (PMID 26668680, 2016).
paraganglioma (6 papers, 2017 to 2021). A benign or malignant neoplasm arising from paraganglia located along the sympathetic or parasympathetic nerves. "In paragangliomas, a mutation in IDH1 was first recorded during the analysis of 365 samples." (PMID 29504908, 2018). "Therefore, we can suggest that frequency of IDH1 mutations may be associated with localization of paragangliomas." (PMID 29504908, 2018). "Interestingly, IDH1 and IDH2 mutated GBM, SDHB deficient pheochromocytoma and paraganglioma are more sensitive to temozolomide (TMZ), and IDH1/2 mutations are con-sidered a good prognostic factor." (PMID 34065551, 2021). "Mutations in some genes have been found only in single patients or families (e.g., MEN1, EGLN1, EGLN2, MDH2, IDH1, BAP1, BRAF); therefore, their role in the formation of paragangliomas/pheochromocytomas cannot be reliably confirmed." (PMID 28187001, 2017).
renal carcinoma (6 papers, 2018 to 2024). A carcinoma arising from the epithelium of the renal parenchyma or the renal pelvis. "It indicates that wild-type IDH1 has some inhibitory effect on renal carcinoma." (PMID 33867843, 2021).
skin cutaneous melanoma (6 papers, 2021 to 2025). "To a lesser extent, we found additional IDH1 mutations in high-methylated skin cutaneous melanomas (SKCM), in accord with previous studies." (PMID 35134107, 2022). "Sample 5 had an NRAS Q61 and IDH1 R132 mutation in the liquid biopsy and the co-occurrence of these mutations is significant (p<0.001) based on the skin cutaneous melanoma TCGA database analysis of mutual exclusivity." (PMID 35494035, 2022). "Hotspot mutations in RQCD1, RAC1 and IDH1 were primarily in non‐acral cutaneous melanomas." (PMID 36219477, 2023).